SULT1A1 (sulfotransferase family 1A member 1)
Diseases named in the same sentence as SULT1A1 in open-access papers (continued):
Sharing a sentence is not in itself a finding about the gene and the disease.
breast carcinoma (continued). "Higher expression of Cp2E1 and Sult1A1 and Sult1A2 in tumors correlated with better survival in breast cancer patients." (PMID 33050543, 2020). "Nowell and Wegman reported that SULT1A1*2/*2 carriers had worse outcome in breast cancer patients treated with tamoxifen compared to both homozygous and heterozygous SULT1A1*1 carriers." (PMID 30120701, 2018). "This is the first study in which the role of 3′-UTR SULT1A1 rs6839 and rs1042157 SNPs on tamoxifen metabolism and clinical outcome in early-breast cancer patients was examined." (PMID 30120701, 2018). "Tamoxifen, an agent that is commonly used to treat breast cancer, is a prodrug that is metabolized by SULT1A1 to its activated metabolite 4-hydroxytamoxifen (4-OH TAM) in the liver." (PMID 27322429, 2016). "In summary, our data demonstrate that the NFI family of transcription factors significantly contributes to the regulation of SULT1A1 expression in human breast cancer cell lines." (PMID 24393253, 2014). "In this study, TFs differentially expressed between low SULT1A1-expressing transformed epithelial mammary cells and high SULT1A1-expressing breast cancer cells have been identified for the first time using a TF Activation Profiling Plate Array assay." (PMID 24393253, 2014). "Our data suggests that SULT1A1 expression is regulated by NFI, as well as SULT1A1 copy number variation in human breast cancer cell lines." (PMID 24393253, 2014). "Understanding the regulation of SULT1A1 expression will facilitate the prediction of drug response in relation to breast cancer prevention and therapy." (PMID 24393253, 2014). "In different human breast cancer and normal epithelial cell lines, SULT1A1 expression was positively correlated with NFI-B and NFI-C." (PMID 24393253, 2014). "Here we examined relationships between the serum levels of tamoxifen, estrogens, follicle-stimulating hormone (FSH), and also determined the genotypes of CYP2C19, 2D6, 3A5, and SULT1A1 in 90 postmenopausal breast cancer patients." (PMID 20565970, 2010). "This is the first meta-analysis that provides significant and contrasting association of SULT1A1 Arg213His polymorphism on cancer risk in distinct sites of TRCs namely UADT and genitourinary and an increased risk for breast cancer in Asians." (PMID 18854828, 2008). "We therefore investigated the genotypes of CYP2D6 and SULT1A1 in 226 breast cancer patients participating in a trial of adjuvant tamoxifen treatment in order to validate the benefit from the therapy." (PMID 15987423, 2005). "We conducted the present study to elucidate the potential role of SULT1A1 genotype alone and in combination with NAT2 genotype as a modifier of susceptibility to breast cancer associated with exposure to tobacco smoke among predominantly premenopausal women." (PMID 15743503, 2005). "As with SULT1A1, several studies have reported links between the UGT1A1 polymorphism and the risk of breast cancer." (PMID 16280036, 2005). "The SULT1A1*1/*1 genotype in combination with NAT2 fast acetylator status, however, appeared to increase breast cancer risk in women exposed to tobacco smoke." (PMID 15743503, 2005). "The hyper-expression of SULT1A1 in breast cancer due to its role in the metabolism of environmental toxins and estrogens, provides the perfect conditions for the development of unique breast cancer targeting molecules." (PMID 38974991, 2024). "In conclusion, our findings suggest that GSTT1 null genotype and SULT1A1 G638A AA genotype could be useful genetic markers for breast cancer prognosis." (PMID 25648141, 2015). "Moreover, SULT1A1 G638A AA genotype significantly increased the chances of HER2 molecular subtype breast cancer when compared to GG genotype (OR = 19.971, 95% CI 1.716-232.480, P = 0.017)." (PMID 25648141, 2015). "Conclusively, our findings suggest that GSTT1 null genotype and SULT1A1 G638A AA genotype could be uselful genetic markers for breast cancer prognosis." (PMID 25648141, 2015).
breast carcinoma (continued). "Therefore, we aimed to investigate possible associations between germline genetic polymorphisms within GSTM1, GSTT1, GSTP1, SULT1A1 and UGT1A1 genes and breast cancer clinicopathological characteristics together with disease progression." (PMID 25648141, 2015). "To date, there are no published data on the effect of the SULT1A1 rs9282861 single nucleotide polymorphism (SNP) on the outcome of adjuvant chemotherapy or the long-term survival of breast cancer patients." (PMID 22708928, 2012). "In this prospective study, our aim was to determine whether SULT1A1 rs9282861 SNP influences the long-term survival of breast cancer patients receiving adjuvant chemotherapy or TAM." (PMID 22708928, 2012). "Firstly, a recent meta-analysis showed that the SULT1A1 R213H polymorphism had no exact effect to increase the risk of breast cancer, but it did increase the risk of breast cancer among postmenopausal women." (PMID 21695180, 2011). "The result indicated that multiple SNP-based approaches rather than a single nucleotide polymorphism-based strategy may provide more exact information on relationship between SULT1A1 and breast cancer." (PMID 20663177, 2010). "SULT1A1 R213 H increased the risk of breast cancer among Asian women but not Caucasian women in recessive model (His/His vs Arg/Arg+Arg/His) which was consistent with the previous studies." (PMID 20663177, 2010). "In the subgroup analysis of different menopausal statue, we surprisingly found that SULT1A1 polymorphism increased the risk of breast cancer among postmenopausal women but not among premenopausal women." (PMID 20663177, 2010). "Although SULT1A1*2 conferred significant increased risk of breast cancer to Asian women (OR=1.91, 95% CI: 1.08, 3.40), it did not confer increased risk to Caucasian women (OR=0.92, 95% CI: 0.71, 1.18)." (PMID 18854828, 2008). "In a previous study we investigated functional polymorphisms in CYP2D6 and SULT1A1 in 226 postmenopausal patients with breast cancer randomised to treatment with or without tamoxifen." (PMID 17244352, 2007). "The distributions of potential risk factors, such as first-degree family history of breast cancer, body mass index, alcohol consumption, menopausal status, parity and breastfeeding, were similar in carriers and noncarriers of the SULT1A1*2 allele." (PMID 15743503, 2005). "We assessed the effect of SULT1A1 genotype on the association between smoking and breast cancer risk, initially comparing ever active smokers with nonsmokers (i.e. passive-only smokers were included in the reference group)." (PMID 15743503, 2005). "In summary, the results of our study do not suggest that there is a strong association between the SULT1A1 Arg213His genetic polymorphism and risk for breast cancer in women who had developed breast cancer by age 50 years." (PMID 15743503, 2005). "Consistent with a role of greater bioactivation of HCAs associated with SULT1A1*1 rather than SULT1A1*2 in carcinogenesis are previous reports of greater risk for breast cancer and prostate cancer associated with intake of well done red meat." (PMID 15743503, 2005). "One study suggested a link between the high-activity SULT1A1*1 allele and early onset of breast cancer as well as the presence of non-breast tumors." (PMID 16280036, 2005). "The overall risk for breast cancer in women who were carriers of at least one SULT1A1*2 allele was not significantly different from that for women with the SULT1A1*1/*1 genotype (adjusted odds ratio 0.83, 95% confidence interval 0.66–1.06)." (PMID 15743503, 2005). "The overall risk for breast cancer among carriers of the SULT1A1*2 allele was not significantly different from that in women with the SULT1A1*1/*1 genotype (adjusted OR 0.83, 95% CI 0.66–1.06)." (PMID 15743503, 2005). "Our data do not suggest a strong influence of SULT1A1 genotype alone or in combination with NAT2 on the risk for breast cancer." (PMID 15743503, 2005).
breast carcinoma (continued). "Associations of breast cancer risk with smoking variables were apparent, but the risk estimates were similar for carriers and for noncarriers of the SULT1A1*2 allele." (PMID 15743503, 2005). "There is no clear evidence that the SULT1A1 Arg213His single nucleotide polymorphism investigated in this study in itself is an important effect modifier of breast cancer risk associated with active/passive smoking among women up to age 50 years." (PMID 15743503, 2005). "There was also no major effect of SULT1A1 genotype in combination with NAT2 acetylator status on breast cancer risk (data not shown)." (PMID 15743503, 2005). "Elucidation of the potential effects of SULT1A1 genotype on a hormone-related cancer, such as breast cancer, is rendered more complicated by the fact that smoking may alter oestrogen levels in the body." (PMID 15743503, 2005). "Nevertheless, we cannot exclude that, because of limitations in statistical power, we were unable to detect a potential weak or moderate association or interaction between SULT1A1 genotype, smoking and breast cancer, independent of NAT2 genotype." (PMID 15743503, 2005). "The association between SULT1A1 Arg213His and breast cancer risk was not significant." (PMID 25225888, 2014). "Kotnis' study showed that the polymorphism of SULT1A1 Arg213His might predispose carriers to lung cancers, protect against colorectal cancers and increase the risk of breast cancer to Asian women but not the Caucasian women." (PMID 20663177, 2010). "We found that SULT1A1 Arg213His had no exact effect to increase the risk of breast cancer (OR = 1.07, 95% CI: 0.97-1.17, P = 0.164), but it did increase the risk of breast cancer among postmenopausal women in the dominant model (OR = 1.28, 95%CI: 1.04-1.58, P = 0.019)." (PMID 20663177, 2010). "Furthermore, although SULT1A1*2 conferred significant increased risk of breast cancer to Asian women (OR=1.91, 95% CI: 1.08, 3.40), it did not confer increased risk to Caucasian women (OR=0.92, 95% CI: 0.71, 1.18)." (PMID 18854828, 2008). "Given the role of SULT1A1 and UGT1A1 in the metabolism of estrogens, we hypothesized that polymorphisms in these genes might be associated with differences in breast tumor characteristics, such as tumor size, tumor grade and age of breast cancer diagnosis." (PMID 16280036, 2005). "Leveraging this data, we sought to further explore the breast cancer selectivity and activation of the AhR/CYP1/SULT1A1 axis of a library of substituted BBQ analogues, in cell line models of the disease." (PMID 38974991, 2024). "Tamoxifen metabolism pathway was found to be enriched in breast cancer patients involving UGT2B15, SULT1A1 and CYP2D6 genes." (PMID 33503040, 2021). "Here, we identified a potential biomarker of TMX resistance, SULT1A1, which is upregulated after TMX treatment in metastatic breast cancers in relapsed patients, in treated breast cancer samples ex vivo and in breast cancer cell lines in vitro." (PMID 32727562, 2020). "Further siRNA transfection assays suggested that SULT1A1 expression is controlled, at least partially, by NFI in breast cancer cells." (PMID 24393253, 2014). "In this descriptive study, correlations were examined between concentrations of tamoxifen metabolites and genotypes for CYP2D6, CYP3A4, CYP3A5, SULT1A1, SULT1A2 and SULT1E1 in 135 patients with estrogen receptor-positive breast cancer." (PMID 23922954, 2013). "In a conclusion, SULT1A1 Arg213His may be associated with breast cancer risk in Asian women and postmenopausal women among all races, although there are no exact effects to increase the risk of breast cancer in premenopausal women." (PMID 20663177, 2010). "The expression of SULT1A1 was readily detectable in primary breast cancer tissues but not in neighboring normal tissues, and SULT1A1 activity was drastically higher in hepatocellular carcinoma patients." (PMID 25514600, 2015).
breast carcinoma (continued). "In the present study we investigated the prognostic and/or predictive value of functional polymorphisms in cytochrome P450 3A5 CYP3A5 (*3), CYP2D6 (*4), sulphotransferase 1A1 (SULT1A1; *2) and UDP-glucuronosyltransferase 2B15 (UGT2B15; *2) in tamoxifen-treated patients with breast cancer." (PMID 17244352, 2007). "In a more recent study by Nowell and colleagues, genetic polymorphism in SULT1A1 and UGT2B15 was analysed in patients with breast cancer treated with or without tamoxifen." (PMID 17244352, 2007). "The aim of the present study was to investigate the genotypes of CYP2D6 and SULT1A1 in breast cancer patients with and without tamoxifen treatment in order to validate the relation between the genotype and the benefit from tamoxifen therapy." (PMID 15987423, 2005). "The data suggest that genetic variation in SULT1A1 and UGT1A1 may influence breast cancer characteristics and might be important for breast cancer prognosis." (PMID 16280036, 2005). "The current study shows no alterations in the SULT1A1 activity in the breast tumor and surrounding tissue explaining that the breast cancer may have little or no role of SULT1A1 mediated nonspecific metabolism of estrogen." (PMID 39132498, 2024). "Moreover, high SULT1A1 provides selective vulnerability to anticancer compounds RITA, AF, and ONC-1 and lay out a rationale for a new combination therapy to overcome TMX resistance in young breast cancer patients." (PMID 32727562, 2020). "We have identified a mechanism of resistance to TMX via hyperactivated SULT1A1, which renders selective vulnerability to anticancer compounds RITA, AF, and ONC-1, and provide a rationale for a new combination therapy to overcome TMX resistance in breast cancer patients." (PMID 32727562, 2020). "It is not clear whether AML samples can be stratified by SULT1A1 expression or whether anti-cancer agents such as tamoxifen, whose activity in breast cancer cells is potentiated by SULT1A1 expression, are also active in SULT1A1-expressing AML cells." (PMID 29254232, 2017). "We found that the expression of the members of detoxification enzyme sulfotransferase family SULT1A1 and SULT1A2, but not other SULT family members, was induced in the metastatic breast cancers as compared to the primary tumors." (PMID 32727562, 2020).
lung carcinoma (9 papers, 2007 to 2023). "Several studies in lung cancer have demonstrated that the variant SULT1A1*2 allele is associated with increased risks of lung cancer, especially for smokers." (PMID 27322429, 2016). "It is known that, mutations in sulfotransferase 1A1 (SULT1A1) are associated with increased lung cancer risk, especially for cigarette smokers." (PMID 26220590, 2015). "Recently, studies have suggested that SULT1A1 HH genotype was associated with an increased risk for some cancers development, such as esophagus, breast, and lung cancer." (PMID 21695180, 2011). "In smokers, EPHX1 Tyr113His and SULT1A1 Arg213His polymorphisms reduced the risk of lung cancer, whereas CYP1A1*2A, CYP1A1*2C and GSTP1 Ile105Val imparted increased risk in non-smokers only." (PMID 22206016, 2011). "The role of SULT1A1 in the biotransformation of tobacco carcinogens and its association with lung cancer has been previously reported." (PMID 18854828, 2008). "And another study on lung cancer in the Chinese population (805 cases and 809 controls) reported that the variant A allele of SULT1A1 was associated with an increased risk of lung cancer (OR, 1.85; 95% CI, 1.44–2.37)." (PMID 17603900, 2007). "Thus in the meta-analysis, in contrast to the seven studies where UADT and lung cancers showed an increased risk association with SULT1A1*2, seven studies on genitourinary cancers showed a protective effect." (PMID 18854828, 2008). "Furthermore, these authors showed that the increased risk of lung cancer related to the variant SULT1A1 genotypes was more pronounced in younger subjects and limited to smokers." (PMID 17603900, 2007). "We then performed quantitative PCR analysis on SULT1A1 mRNA in two sensitive (H460 and H157) and two resistant (H322 and H1299) lung cancer cell lines." (PMID 25514600, 2015). "CYP1A1*2A and EPHX1 His139Arg polymorphisms were associated with increased risk to lung cancer in dominant genetic model, whereas EPHX1 Tyr113His and SULT1A1 Arg213His imparted reduced risk in recessive genetic model." (PMID 22206016, 2011). "To determine whether SULT1A1 expression has a causal relationship with NSC-743380 susceptibility, we transfected NSC-743380 resistant H1299 lung cancer cells with a plasmid expressing SULT1A1 together with a plasmid expressing GFP." (PMID 25514600, 2015). "Individually, CYP1A1*2A polymorphism was significantly associated with increased lung cancer risk (OR = 1.69;95%CI = 1.11–2.59,p = 0.01), whereas EPHX1 Tyr113His and SULT1A1 Arg213His conferred reduced risk (OR = 0.40;95%CI = 0.25–0.65,p<0.001 and OR = 0.51;95%CI = 0.33–0.78,p = 0.002 respectively)." (PMID 22206016, 2011). "However, others studies reported that SULT1A1*2 isoform could confer not statistically significant reduced risks to bladder cancer and colorectal cancer, as well as a statistically significant lung cancer risk reduction in heterozygous individuals." (PMID 23264952, 2012). "MDR analysis identified two distinct predictor models for the risk of lung cancer in smokers (tobacco chewing, EPHX1 Tyr113His, and SULT1A1 Arg213His) and non-smokers (CYP1A1*2A, GSTP1 Ile105Val and SULT1A1 Arg213His) with testing balance accuracy (TBA) of 0.6436 and 0.6677 respectively." (PMID 22206016, 2011).
colorectal cancer (8 papers, 2007 to 2025). A primary or metastatic malignant neoplasm that affects the colon or rectum. "Though research has shown that genetic variants of Sult1A1 can increase risk of breast or colorectal cancer, few studies have found differences in depressive disorders." (PMID 24826212, 2014). "A number of case-control studies were conducted to investigate the association of SULT1A1 R213H polymorphisms with colorectal cancer (CRC) in humans." (PMID 21695180, 2011). "For instance, in cancer research, the expression levels of SULT1A1 are closely associated with the occurrence and progression of tumors, including colorectal cancer, by influencing tumor growth and metastasis through the regulation of endogenous hormone and carcinogen metabolism." (PMID 40070478, 2025). "Our objective was to measure the interactions between common polymorphisms of P450 (CYP1A2, CYP1B1, CYP2E1), GSTM1 and T1, SULT1A1 and cigarette smoking in colorectal cancer (CRC)." (PMID 17603900, 2007).